Y_RNA (Y RNA )
Gene: Miscellaneous RNA gene on chromosome 5 (132,945,342 to 132,945,454, forward strand). Ensembl gene ENSG00000202417.
Homologues: Orthologues: chimpanzee Y_RNA (100% identical), macaque Y_RNA (94% identical). Paralogues in human: RNY1 (81% identical), Y_RNA (81% identical), Y_RNA (80% identical), Y_RNA (79% identical), Y_RNA (78% identical), Y_RNA (77% identical), RNY1P11 (76% identical), Y_RNA (76% identical), Y_RNA (75% identical), Y_RNA (74% identical), RNY1P8 (73% identical), Y_RNA (73% identical), and 93 more.